ENSG00000251999
Gene: Small nucleolar RNA gene on chromosome 7 (32,791,814 to 32,791,946, forward strand). Ensembl gene ENSG00000251999.
Homologues: Orthologues: rat LOC120102627 (72% identical). Paralogues in human: SNORA31B (80% identical), SNORA31 (65% identical).